MYC (MYC proto-oncogene, bHLH transcription factor)
Diseases named in the same sentence as MYC in open-access papers (continued):
Sharing a sentence is not in itself a finding about the gene and the disease.
cancer (continued). "TERT, MKI67, and MYC mRNA expression was higher in cancer tissues than in non-HCC liver samples." (PMID 22912812, 2012). "Besides MYC and CCNE1, there are multiple genes in these regions, which could contribute to a growth advantage for the cancer cell." (PMID 21781349, 2011). "Furthermore, MYC is necessary for the invasion and metastasis of cancer cells in experimental xenografts independent of its effects on proliferation and survival." (PMID 22075943, 2011). "Our results are in agreement with studies demonstrating that c-MYC sensitize a variety of cells to different cytotoxic treatments, and that absence of c-MYC expression might confer resistance to anti-cancer agents." (PMID 19134217, 2009). "We then analyze activated upstream regulators by Ingenuity Pathways Analysis (IPA) and the data revealed the top 3 upstream regulators: MYC, lipopolysaccharide (LPS) and 1,2-dithiol-3-thione (D3T), suggesting that gram-negative bacteria could be an important modulator of cancer progression in OSCC." (PMID 39743544, 2025). "Hence, reducing MYC activity limits the cell’s ability to cope with replication stress, and when this is coupled with inhibition of key DNA repair pathways such as ATR/CHK1, WEE1, DNA-PKcs, or PARP, cancer cells can be pushed toward irreversible genomic instability." (PMID 41561634, 2025). "The activation of cellular glucose metabolism by the MYC oncoprotein has been shown to enhance the production of NADPH, which may serve as a reducing agent to facilitate the resolution of disulfide bonds, thus suppressing disulfidptosis in cancer cells characterized by high levels of SLC7A11." (PMID 41343099, 2025). "However, in cancers cells, including MM cells, this cycle is disrupted due to the inhibition of PP2A activity or enhanced expression/activity of numerous kinases involved in pro-survival signalling and cell cycle regulation, leading to high pS62 MYC levels and MYC stabilization." (PMID 40241199, 2025). "However, stemness-related signatures, such as MYC targets, displayed both positive and negative enrichment in integrinScore-high groups in a similar number of cancer types, indicating intrinsic biological differences among distinct cancer types." (PMID 39436262, 2024). "Moreover, by using a conditional MYC system, we demonstrate that some of the genes previously identified as MYC-SL, like Mtor66, Cdk967, or Wdr568, may not be specific for MYC-driven cancers." (PMID 38302473, 2024). "Furthermore, as a downstream target of the UBE2O/AMPK/mTOR pathway, MYC transcriptionally promotes UBE2O expression, thus constituting a positive feedback loop that promotes cell proliferation and epithelial–mesenchymal transformation (EMT) in many types of human cancers." (PMID 39272922, 2024). "Yet although these specific mechanisms have been shown to be important for specific oncogene expression, such as MYC, little is known about how non-canonical translation initiation factors driving these mechanisms may contribute to cancer development and progression." (PMID 38129098, 2024). "Thus, proper manipulation of SP1, HIF-1, and MYC by appropriate agents could have a strong negative impact on cancer development." (PMID 37998757, 2023). "However, given the context-specific nature of MYC-driven metabolic alterations and TET activity, the contribution of α-KG-mediated DNA demethylation to reductive carboxylation should first be established in other cancers before pharmacologic studies are undertaken." (PMID 35740646, 2022).
cancer (continued). "Likewise, we could not detect any effect on the transcript abundance of SAFB, and MYC protein expression correlated with SAFB protein but not with SAFB mRNA across a large panel of cancer cells lines from the CCLE." (PMID 35499080, 2022). "Considering that c-Myc functioned as a key downstream effector in aberrantly activated FGFR signaling in cancer 21 and that FGF-induced vascular development was dependent on endothelial glycolysis via MYC/HK2 43, we also tested whether HK2 downregulation by FGFRi was c-Myc dependent in this study." (PMID 36168616, 2022). "However, reports describing widespread 3′UTR shortening in cancers suggest that these interactions may not exist in cancer cells, contributing to the overexpression of MYC in multiple cancers often in the absence of genetic aberrations." (PMID 34937878, 2022). "However, in cancer cells expressing oncogenic forms of KRAS, the balance between the phosphorylation-dephosphorylation states of MYC is shifted toward an increased phosphorylation at Ser 62, thus reducing the amount MYC that undergoes ubiquitination and degradation." (PMID 36581205, 2022). "Importantly, while the c-MYC protein is overexpressed in ∼70% of human cancers, typically only ~20% of tumors harbor c-MYC gene amplifications or translocations and thus it remains possible that aberrant c-MYC turnover/degradation may account for this discrepancy." (PMID 35008511, 2021). "The synthetic lethality seems specific to MYC overexpressing cells as it could not be substituted by a variety of oncogenic manipulations and synthetic lethality was diminished by RNAi-mediated depletion of MYC in human cancer cell lines." (PMID 33760847, 2021). "However, in cancer, the carcinogenic mechanism of KDM4B is due to an abnormal increase in its expression, resulting in activation of multiple oncogene signaling pathways by histone demethylation, such as binding with MYC, AR or ER to promote the expression of downstream genes." (PMID 35186950, 2021). "Finally, CNAtra successfully detected the previously-reported focal amplifications of MYC (NCI-H82) and MYCN (CHP-212, IMR-32) loci as well as homozygous focal deletions of BANK1/4q24 (NCI-H82), LKB1/STK11 (A427), and p16INK4a/CDKN2A (A427) loci in respective cancer cell lines." (PMID 32299346, 2020). "Therefore, exploring the functional connection between MYC and SWI/SNF can be considered as a major factor in understanding the role of SWI/SNF in controlling tissue-specific gene expression programs and in developing strategies for novel therapies for MYC dependent cancers." (PMID 31932624, 2020). "However, certain types of cancer, like MYC-driven prostate cancer, are refractive to PI3K-AKT-mTORC inhibitors, but treatment with CX-5461 in combination with an inhibitor of PIM kinase, frequently upregulated in these cancers, showed improved therapeutic efficiency." (PMID 31973211, 2020).
cancer (continued). "Thus, our results demonstrate the utility of measuring MYC expression as a pharmacodynamic marker of BET bromodomain inhibitor response and demonstrate the need to develop strategies to co-target MYC along with BET bromodomain inhibition in resistant cancer cells." (PMID 30846826, 2019). "Additional genes regulated by LEF1 in MYC-transformed cells may be involved in other metabolic and non-metabolic pathways that are important for the deregulated proliferation or other aspects of cancer cell fitness." (PMID 31623618, 2019). "Moreover, therapies that target the vulnerability of MYC-driven cancers rather than its direct suppression may avoid the toxicity that would be expected in normal tissues." (PMID 30458889, 2018). "Furthermore, reducing the concentration of lactate in the TME would limit cancer cells’ inward uptake of lactate through MCT-1, which was suggested to indirectly increase glutaminolysis by upregulating the expression of the glutamine transporter ASCT2 in a MYC and HIF-2α dependent manner." (PMID 28969664, 2017). "Although the mechanisms are not completely understood, replication stress in cancer cells may be the result of activation of oncogenes such as resistance to audiogenic seizures (RAS), v-myc avian myelocytomatosis viral oncogene homolog (MYC), cyclin-dependent kinases (CDKs) and CYCLINs." (PMID 28067787, 2017). "In addition to the inflammation pathway, several cancer-related pathways were identified from the global NSAIDs-regulating miRNA-gene subnetwork, including cell cycle (CDK6, CCND1, CCKN1A, and E2F1), proliferation (MYC), apoptosis (BCL2) and angiogenesis (VEGFA)." (PMID 27329603, 2016). "Additionally, the IL-6- and/or MYC-driven mouse models of human BL and MM used in this study may lend themselves to the biological validation of CDKN1A and FANCD2 as molecular targets for new approaches to cancer therapy and prevention." (PMID 25838973, 2015). "To further investigate whether cancer cells cultured in a 3D matrigel microenvironment acquire stem cell–like characteristics when compared with 2D monolayer cells, we measured the expressions of the stem cell markers OCT4, SOX2, NANOG, c-MYC and LIN28 in both 2D- and 3D-cultured A549 cells." (PMID 25883172, 2015). "To assess the requirement for continued MYC activity and whether PIM expression is sufficient to maintain leukemogenesis without the expression of MYC, we de-induced MYC expression at a pre-leukemic stage of cancer development in the mice by giving doxycycline containing feed." (PMID 25238262, 2014). "We do not yet know the totality of genes regulated by MYC in cancers such as SCCOHT, nor do we understand the influence that SWI/SNF has on MYC activities in this context." (PMID 40647552, 2025). "In this regard, MYC amplification and MYC overexpression do not drive ERCC6L dependence in a pan-cancer analysis of data from the DepMap portal (DepMap Public 23Q2+Score, Chronos)." (PMID 38253636, 2024). "Results showed that STK16 overexpression upregulated the expression levels of c-MYC, GLUT1, and CDK4 in c-MYC WT cancer cells, but not in c-MYC S452A cancer cells." (PMID 38622518, 2024). "Further analysis of cancer cell lines and three noncancerous cell lines as controls revealed that sensitivity to TAK-981 correlated with basal MYC mRNA expression levels." (PMID 38992694, 2024).
cancer (continued). "As an MYC target gene, JPO1/CDCA7 is also frequently over-expressed in human cancers, but its expression in gliomas has not been studied." (PMID 37510310, 2023). "In different cancers, c-MYC has been found regulated by different ubiquitin-specific proteases (USPs), but to date, the role of USPs in c-MYC regulation has not been investigated in DLBCL." (PMID 36985413, 2023). "Focal adhesion kinase (FAK) promoted the aerobic glycolysis of cancer cells and fibroblasts, while FAK-related non-kinase kinase (FRNK) inhibited the aerobic glycolysis of HSC by inhibiting the FAK/Ras/c-MYC/ENO1 pathway, thereby improving liver fibrosis." (PMID 37663261, 2023). "CFP1 upregulated expression of β-catenin, LEF1, TCF1/TCF7, c-MYC, TGFBR3, and TGFB1, and the cancer-promoting effects of CFP1 were not completely repressed by pathway inhibitors." (PMID 37735441, 2023). "Given the wide oncogenic role of MYC, it is not surprising that CCAT1-L is frequently expressed at elevated levels in many cancer types." (PMID 36901971, 2023). "With super-enhancers hijacking essential transcription factors (MYC) and chromatin remodelers (NSD2), it may not be surprising that the increased expression and presence of the translated protein could indirectly drive the appearance of H3K4me3-BD over other cancer-associated genes." (PMID 34933939, 2022). "Regardless of MYC, a genetic screen in Drosophila identified that FBXW7 depletion impaired autophagy, which could explain the accumulation of dysfunctional mitochondria that is seen in FBXW7‐deficient cancer cells, rendering them sensitive to therapies further compromising mitochondrial function." (PMID 35861150, 2022). "Overall, 13 cancer hallmarks were significantly upregulated in the MCL cells from patient B (the non-responder), including MYC, OXPHOS, BCR, mTORC1, cell cycle, and PI3K/AKT/mTOR signaling." (PMID 34001881, 2021). "Although no data on the expression levels of endogenous MYC have been reported in living cells, three derivatives (ANMP, ANDP and ANTP) showed promising antiproliferative activity in selected cancer cell lines but not in normal human dermal fibroblasts." (PMID 34073075, 2021). "Of course, a PARP inhibitor is not originally designed to inhibit MYC activity per se, but our finding suggests that inhibiting PARP activity curbs neoplastic MYC activity only when cancer cells acquire cisplatin resistance." (PMID 34948122, 2021). "Using combined pan-cancer studies, moderately positive correlations of CCT2 mRNA were found with MYC, CDK2, CDK4, CCNE1 but not CCND1 (slight negative correlation)." (PMID 33996588, 2021). "One of our important findings is that in contrast to cancer tissues, chemical inhibition of Gln metabolism with GLS1 and MYC inhibitors in BPH cells did not result in radiosensitization or even increase cell radioresistance." (PMID 34335968, 2021). "The correlation of MYC with TERT and DKC1 in cancers suggests that oncogene activation is one of the important events that initiates cancer-specific non-telomeric functions of TERT and DKC1." (PMID 33599797, 2021). "Different from cancer cells, we did not observe the enrichment of either E2F1 or MYC at this region in normal RWPE1 cells, whereas MYC showed obvious enrichment at this SNP containing region when the cells were treated with DHT." (PMID 34858826, 2021). "Oncogenes, such as MYC, have a transcriptional dependency on BRD4 and recent findings suggest additional non-transcriptional functions of BRD4 in cancer." (PMID 33322239, 2020). "Even though the amplification of 8q24 has been demonstrated in many studies, pan-cancer analysis of the MYC-PVT1 dysregulation in different cancers yielded a strong correlation between PVT1 and MYC in tumor patients lacking 8q24 locus amplification." (PMID 32117705, 2020). "Cancer cell-intrinsic properties like proliferation, apoptosis or invasiveness were not different between the non-metastatic MYC-HCC and the metastatic MYC/Twist1-HCC." (PMID 31933479, 2020).
cancer (continued). "There was no survival difference among either MYC targets v1 or v2 high and low groups in subtypes of TNBC or HER2-positive cancer." (PMID 33143224, 2020). "More importantly, this ligand showed cytotoxicity against cancer cell lines overexpressing c-MYC but not against normal cells, suggesting reduced side effects based on G4 selectivity on c-MYC." (PMID 32257105, 2020). "A recent report of super-enhancers at the c-MYC oncogene locus, which are not active in normal colon cells but are active in HCT116 cells, represents another example of cancer-specific enhancers." (PMID 31118064, 2019). "This anti-correlation between MYC and BCL2 appears to be an exception rather than the rule since we primarily found a positive correlation between MYC and BCL2 expression in the pan-cancer CCLE cohort." (PMID 31375684, 2019). "Expression of B cell genes by hMYC cancers was unexpected, because B-ALL has never been described by several laboratories—including ours—that study transgenic Myc/MYC zebrafish." (PMID 30111845, 2019). "In the present study, we found that BIO induced the expression of the cancer stem cell markers EpCAM, CD44, KRT19, and MYC above the levels seen in MeBIO controls without inducing cytotoxicity." (PMID 30177680, 2018). "Specifically nuclear MYC was found to be upregulated in many PIN lesions and most carcinomas in the absence of gene amplification." (PMID 29671777, 2018). "Finally, much like MYC, AMPK functions as a conditional tumor suppressor and as a contextual oncogene—thus, a dysfunction of the LKB1/AMPK signaling pathway could rewire the circadian epigenome and rhythmic gene expression to contribute eventually to cancer development." (PMID 28674522, 2017). "However, using B cell specific Chk1 knock-out mice we could show that Eμ-MYC driven tumors highly depend on CHK1 as none of our Mb1-Cre Chk1fl/− mice expressing the MYC transgene developed cancer over an observation period of one year and disease onset was found delayed in Chk1+/− mice." (PMID 29167438, 2017). "Moreover, when regarding the actual numbers of cancer-specific death events, we noted that only one of 22 patients (4.5%) with strong MYC staining suffered a cancer-related death, compared to 9 of 67 (13.4%) cases with absent MYC staining and 18 of 110 (16.4%) cases with intermediate MYC staining." (PMID 29180625, 2017). "Pharmacologic inhibition of MYCN oncoprotein is therefore of great interest in pediatric cancer; however, direct targeting of MYCN, or MYC oncoproteins in general, has not yet delivered viable therapeutics to the clinic." (PMID 27438153, 2016). "In cancer cell lines, CaMKIIγ was positively correlated with OCT4 and NANOG expression, but was not correlated with MYC or KLF4." (PMID 25965829, 2015). "For STAT1 and MYC, data were available for MET and Non-Met cancers, but not for the non-cancer model." (PMID 24612742, 2014). "We then tested for preferential binding of the AP1/MYC pair, and again saw results consistent with this pair acting in both MET and Non-MET cancer models." (PMID 24612742, 2014). "Analysis of data in The Cancer Genome Atlas shows negative correlations between SALL2 and c-MYC expression in four common solid tumor types." (PMID 23029531, 2012). "Here, we tested the correlation between mRNA expression of MYC and several alternatively spliced forms of TCF7L2 in 117 non-cancer colon samples." (PMID 19895682, 2009). "In samples with this amplicon, MYC, PVT1 and TMEM75 do not show CNA-specific expression although the scores for MYC are suggestive (ANOVA FDR 0.02, Cancer with CNA vs. Cancer without CNA FDR 0.10, log2 ratio 0.75)." (PMID 19419571, 2009). "This suggested that the inhibition of SP1, MYC, and HIF1A should have strong negative impacts on the expression of stem cell- or EM transition-related cellular mechanisms that play important roles in the progression of cancer cells." (PMID 39590335, 2024).